RNU1-109P (RNA, U1 small nuclear 109, pseudogene)
Gene: Small nuclear RNA gene on chromosome 18 (797,989 to 798,135, reverse strand). Ensembl gene ENSG00000206687.
Homologues: Orthologues: chimpanzee U1 (97% identical), macaque U1 (92% identical), rat U1 (61% identical), zebrafish U1 (61% identical), pig U1 (61% identical), zebrafish U1 (60% identical), zebrafish U1 (59% identical), dog U1 (58% identical), zebrafish U1 (58% identical), zebrafish U1 (57% identical), guinea pig U1 (56% identical), zebrafish U1 (56% identical), and 1 more. Paralogues in human: RNU1-1 (86% identical), RNU1-2 (86% identical), RNU1-27P (86% identical), RNU1-28P (86% identical), RNU1-3 (86% identical), RNU1-4 (86% identical), RNU1-78P (86% identical), RNVU1-18 (86% identical), RNVU1-29 (86% identical), U1 (86% identical), RNVU1-28 (85% identical), RNVU1-7 (85% identical), and 133 more.